CXCR4 (C-X-C motif chemokine receptor 4)
Diseases named in the same sentence as CXCR4 in open-access papers (continued):
Sharing a sentence is not in itself a finding about the gene and the disease.
periodontal disease (3 papers, 2016 to 2024). "Additionally, CXC chemokine receptor 4 (CXCR4) was found to be related to periodontal diseases, especially in context of periodontal pathogens as Porphyromonas gingivalis." (PMID 34925639, 2021). "Moreover, P. gingivalis is an important factor of SDF-1α/CXCR4 expression by HGFs in periodontal tissue, and the increase of SDF-1α and CXCR4 expression might be related to the progression of periodontal disease." (PMID 27449062, 2016). "Participants with periodontal diseases have higher levels of SDF-1α and CXCR4 compared to healthy participants, and SDF-1α may recruit host-defensive cells as well as PDL cells to sites of inflammation to be involved in immune surveillance, wound healing and tissue repair." (PMID 27449062, 2016).
pleural mesothelioma (3 papers, 2017 to 2023). A neoplasm that arises from the mesothelial cells of the pleura. "This is the first report of in vivo imaging of CXCR4 expression in humans with pleural mesothelioma." (PMID 29228566, 2017). "The aim of this pilot study was to assess the feasibility of non-invasive imaging of CXCR4 in patients with pleural mesothelioma." (PMID 29228566, 2017). "In contrast to past reports, our data suggest widely absence of CXCR4 expression in pleural mesothelioma." (PMID 29228566, 2017).
pulpitis (3 papers, 2017 to 2023). Inflammation of the dental pulp. "These aroused our attention to probe the interaction of PECAM1 and CXCR4 in pulpitis progression, and the potential molecules involved." (PMID 33425898, 2020). "A transcription factor myocyte-enhancer factor 2 (MEF2C) was predicted and validated as a positive regulator of either PECAM1 or CXCR4, which activated the NF-κB signaling pathway and promoted pulpitis progression." (PMID 33425898, 2020). "Collectively, it can be concluded that MEF2C promotes transcription and interaction between PECAM1 and CXCR4, therefore promoting inflammatory responses in pulpitis samples." (PMID 33425898, 2020). "Subsequently, we further examined the expression of and correlation between MEF2C and PECAM1 and CXCR4 in the dental tissues of rats in the Sham and Pulpitis groups." (PMID 33425898, 2020). "The high-expression profiles of PECAM1 and CXCR4 were validated in our rat models with pulpitis and in LPS-induced HDPFs." (PMID 33425898, 2020). "Importantly, PECAM1 and CXCR4 were analyzed to be highly expressed and highly interacted in pulpitis, while the B-cell signaling pathways were positively correlated with PECAM1 expression." (PMID 33425898, 2020). "CXC-chemokine receptor 4 (CXCR4) combined with recombinant platelet/endothelial cell adhesion molecule (PECAM1) could regulate inflammatory cell infiltration by activating the Nuclear Factor-kappa B (NF-κB) signaling pathway in pulpitis." (PMID 37238161, 2023). "In this paper, a Limma R Package analysis based on a Gene Expression Omnibus (GEO) pulpitis dataset GSE16134 suggested a possible interaction between PECAM1 and chemokine receptor 4 (CXCR4)." (PMID 33425898, 2020). "Taken together, by inducing pulpitis models in animals and HDPCs, this study was performed to evaluate the potential functions of PECAM1 and CXCR4 in pulpitis development and the possible involvement of the NF-κB signaling pathway, and to explore the potential regulatory network as well." (PMID 33425898, 2020). "Our findings provide direct evidence that SDF-1/CXCR4 axis induces hDPSCs migration through FAK/PI3K/Akt and GSK3β/β-catenin pathways, implicating a novel mechanism of dental pulp repair and a possible application of SDF-1 for the treatment of pulpitis." (PMID 28067275, 2017).
Right ventricular hypertrophy (3 papers, 2011 to 2025). In this case the right ventricle is more muscular than normal, causing a characteristic boot-shaped (coeur-en-sabot) appearance as seen on anterior- posterior chest x-rays. "As shown in the results, two weeks of treatment with the CXCR4 inhibitor significantly decreased hypoxia-induced pulmonary pressure, right ventricular hypertrophy and vascular remodeling of pulmonary arteries in rats." (PMID 21294880, 2011). "The CXCR4 inhibitor also significantly decreased right ventricular hypertrophy, showing a decrease in the ratio of RV/(LV+S) in the rats treated with the CXCR4 inhibitor as compared with the hypoxic control animals." (PMID 21294880, 2011). "The present study showed that baicalin was effective in reducing RVSP, right ventricular hypertrophy, SDF-1/CXCR4 expression and PI3K/AKT pathway activation in PAH, thereby partially reversing pulmonary vascular remodeling." (PMID 28774332, 2017). "Invasive hemodynamic parameters, the right ventricular hypertrophy index, pulmonary congestion, the pulmonary arterial remodeling index, blood gas parameters, A2AR expression, and the expression of SDF-1/CXCR4/PI3K/protein kinase B (PKB; AKT) signaling components were measured." (PMID 28774332, 2017).
skin cancer (3 papers, 2015 to 2022). "Hence, the SDF-1/CXCR4 chemokine pathway is a novel therapeutic target in the prevention of skin inflammation and UV-induced skin cancer." (PMID 26296527, 2015).
tauopathy (3 papers, 2018 to 2019). Neurodegenerative disorders involving deposition of abnormal tau protein isoforms (tau proteins) in neurons and glial cells in the brain. "In a mouse model of tauopathy, CXCR4 and functionally associated genes were altered in the presence of tau pathology." (PMID 29636460, 2018). "Furthermore, in a mouse model of tauopathy, expression of CXCR4 and functionally associated genes was significantly altered in regions of the mouse brain that accumulate neurofibrillary tangles most robustly." (PMID 29636460, 2018). "Furthermore, within the tauopathy mouse model, we found a strong association between CXCR4 and TMEM119 and AIF1 within the hippocampus." (PMID 29636460, 2018). "CXCR4 expression is increased in human neurodegenerative diseases and in mouse models of tauopathies." (PMID 31396262, 2019). "More specifically, up-regulation of CXCR4 in in a mouse model led to abnormal signaling in microglia and tauopathy." (PMID 31068785, 2019).
testicular germ cell tumor (3 papers, 2016 to 2023). A germ cell tumor arising from the testis. "CXCR4 and its ligand are responsible for the maintenance of adult stem cell niches, stimulate the invasive migration of testicular germ cell tumor (TGCT) cell lines in vitro, and selectively influence seminoma migration and metastasis." (PMID 27070582, 2016). "Other biomarkers have been studied for their prognostic/predictive value in testicular germ cell tumors, including MIB-1, CXCL12, CXCR4 and beta-catenin." (PMID 32758242, 2020). "We aimed to assess the prognostic value of previously suggested biomarkers, related to proliferation (MIB-1 and TEX19) and to immune microenvironment (CXCL12, CXCR4, beta-catenin and MECA-79) in a surveillance cohort of stage I testicular germ cell tumor patients." (PMID 32758242, 2020).
Thrombocytosis (3 papers, 2021 to 2024). Increased numbers of platelets in the peripheral blood. "The increase in lymphocytes post-HCD feeding for 8 weeks could be due to HCD, which interferes with the bone marrow stromal cell–derived factor-1:CXCR4 axis, resulting in lymphocytosis, thrombocytosis, and hematopoietic progenitor cells mobilization." (PMID 38207245, 2024). "This cell-to-cell contact is dependent on binding of the chemokine-receptor CXCR4 to its ligand CXCL12, and so it is conceivable that neutrophilia can exacerbate thrombocytosis in ET." (PMID 37051288, 2023).
uveitis (3 papers, 2011 to 2024). An inflammatory process affecting a part of or the entire uvea. "Its target receptor, CXCR4, has previously been shown to be important in leukocyte trafficking in both an ovalbumin-induced uveitis model and an adoptive transfer EAU model." (PMID 39198470, 2024). "Analysis of the scRNA-seq data indicated that inhibition of PIM1 and CXCR4 might be the critical beneficial mechanism of DMF in uveitis." (PMID 38684986, 2024). "The intercellular communication analysis in our study among the retina cells predicted that Cxcl12-Cxcr4 was a significant ligand-receptor pair that was mainly sent by VECs and acted on immune cells, indicating the involvement of CXCR4 in ocular infiltration of immune cells during uveitis." (PMID 38684986, 2024). "Therefore, our study indicated that PIM1 and CXCR4 might be critical mediators of the effects of DMF in uveitis." (PMID 38684986, 2024). "To explore the impact of DMF on ocular T cell infiltration during uveitis, we integrated retinal immune cells of EAU mice with CDLN cells from each group and observed that T cells in the retina of EAU mice expressed the highest level of Cxcr4 and Pim1." (PMID 38684986, 2024). "Thus, DMF treatment could inhibit ocular infiltration of Teff cells in uveitis and this effect might depend on its inhibition of PIM1 and CXCR4 expression." (PMID 38684986, 2024).
vitiligo (3 papers, 2022 to 2023). Generalized well circumscribed patches of leukoderma that are generally distributed over symmetric body locations and is due to autoimmune destruction of melanocytes. "Some classic signaling pathways of vitiligo were also enriched, including melanocyte development and pigmentation signaling and the CXCR4 signaling pathway." (PMID 35252347, 2022). "Studies examined patient-derived melanocytes and skin samples, and found a significant increase in the expression of epidermal melanocyte-derived CXCL12, surrounded by CXCR4+ cells in early vitiligo." (PMID 35096274, 2022). "A more recent study revealed that 5-fluorouracil (5-FU) significantly increased the CXCL12 level in the vitiligo skin, and blocking the CXCL12/CXCR4 pathway, in turn, inhibited melanocyte migration." (PMID 35096274, 2022).
22q11.2 deletion syndrome (2 papers, 2018 to 2020). 22q11.2 deletion syndrome (DS) is a chromosomal anomaly which causes a congenital malformation disorder whose common features include cardiac defects, palatal anomalies, facial dysmorphism, developmental delay and immune deficiency. "Recently, work in chick suggested that signalling via CXCR4 in neural crest cells (NCCs) has a role in the 22q11.2 deletion syndrome (22q11.2DS), a disorder where haploinsufficiency of the transcription factor TBX1 is responsible for the major structural defects." (PMID 30408103, 2018).
acute graft versus host disease (2 papers, 2010 to 2024). A syndrome of immunologically mediated tissue damage that may occur following an allogeneic transplant, usually affecting the skin, liver, and GI tract. "Plerixafor, a small molecule inhibitor of CXCR4, has exhibited good efficacy in mobilizing hematopoietic stem cells from donors, accompanied by a lower incidence of acute GVHD and cytomegalovirus (CMV) viremia." (PMID 39840040, 2024). "Cytotoxic γδT cells migrate to the target organs of acute GVHD through CXCR4 mediation." (PMID 39840040, 2024). "In addition, CD4+ T cells, rather than CD8+ T cells, also depend on the migration of the CXCL12/CXCR4 axis to target organs in acute GVHD mice." (PMID 39840040, 2024).
acute liver failure (2 papers, 2020 to 2023). Rapid deterioration of liver function causing encephalopathy and coagulopathy. "Significantly, overexpression of CXCR-4 in MSCs enhanced the therapeutic effect of MSC transplantation on acute liver failure by activating the PI3K/Akt signaling pathway." (PMID 37667383, 2023).
adenocarcinoma of the esophagus (2 papers, 2006 to 2022). "We performed a preclinical assessment of fluorescence imaging and endoscopy using a novel CXCR4-targeted fluorescent peptide ligand in the L2-IL1B mouse model of Barrett’s esophagus." (PMID 35006394, 2022). "This preliminary preclinical study shows that CXCR4-targeted fluorescence endoscopy using MK007 can detect dysplastic lesions in a mouse model of Barrett’s esophagus." (PMID 35006394, 2022).
adenopathy (2 papers, 2019 to 2020). "Patients with CXCR4 mutations present with a significantly lower rate of adenopathy, and those with CXCR4 nonsense mutations have increased bone marrow disease, serum IgM levels, and/or symptomatic hyperviscosity." (PMID 35309816, 2019).
age-related macular degeneration (2 papers, 2012 to 2022). Age-related loss of vision in the central portion of the retina (macula), secondary to retinal degeneration. "CXCR4 expression in RPE cells increased in aged human eyes and in eyes with age-related macular degeneration." (PMID 36262888, 2022).
alcoholic hepatitis (2 papers, 2020 to 2022). Acute hepatitis resulting from ingestion of alcohol. "In accordance with the presented data, CXCR4 and CXCR7 blockade decreased the release of inflammatory chemokines in acute pulmonary inflammation and human alcoholic hepatitis." (PMID 32210974, 2020).
allergic asthma (2 papers, 2022 to 2024). A asthma with a basis in a pathological type I hypersensitivity reaction. "Furthermore, angiogenesis-associated factors such as VEGF, SDF-1, and CXCR4 were also significantly elevated in the serum of the OVA-induced allergic asthma mice." (PMID 38913666, 2024). "Additionally, we found that the administration of rosuvastatin was effective in decreasing the levels of VEGF, SDF-1, and CXCR4 in the serum of mice with chronic allergic asthma." (PMID 38913666, 2024).
alopecia (2 papers, 2024 to 2026). Hair loss usually from the scalp. "This series of experimental designs is poised to unveil the specific mechanisms of the SDF-1/CXCR4 signaling axis in chronic stress-induced hair loss, providing crucial insights for further research in treating stress-induced hair loss." (PMID 39456139, 2024). "In this study, we aimed to explore the mechanisms of the SDF-1/CXCR4 signaling axis in a mouse model of stress-induced hair loss." (PMID 39456139, 2024). "Activating the SDF-1/CXCR4 signaling axis and relevant signaling pathways may promote hair follicle growth and recovery, offering new hope for patients with hair loss." (PMID 39456139, 2024). "Clinically, this research could form the theoretical foundation for developing drugs targeting the SDF-1/CXCR4 signaling pathway, potentially offering more effective treatment options for patients with hair loss." (PMID 39456139, 2024). "The SDF-1/CXCR4 axis may serve as a potential therapeutic target for stress-induced hair loss." (PMID 39456139, 2024). "Treg-expressed CXCR4 contributes only a minor, context-dependent influence on hair growth, often overwhelmed by the potent pathological signals in alopecia." (PMID 42064044, 2026). "Our research further reveals the regulatory mechanism of the SDF-1/CXCR4 signaling axis in the PI3K/Akt and JAK/STAT signaling pathways, providing new theoretical support for treating stress-induced hair loss." (PMID 39456139, 2024). "However, the role of the SDF-1/CXCR4 axis in CUS-induced hair loss pathology remains unclear." (PMID 39456139, 2024).
anaplastic carcinomas (2 papers, 2005 to 2022). "CXCR4 was present in 12.5% of medullary and 25% of anaplastic carcinomas." (PMID 35799158, 2022).
aneurysm (2 papers, 2025). Bulging or ballooning in an area of an artery secondary to arterial wall weakening. "We found that this axis played a role in cell–cell interactions, which is confirmed by the increased expression of Cxcr4 in the aneurysm and increased expression of Ackr3 in the vascular wall and adventitia." (PMID 40440080, 2025). "Hypomethylation of several genes, including CXCR4, OSM, GSTA4, MAP3K10, ADAMTS, PTBP1, and PNPLA6,61, –63,65,67,71 has been identified as being associated with the aneurysm formation." (PMID 41342741, 2025). "By immunostaining, we confirmed the increased expression of Cxcr4 mostly in the aneurysm of the AAA group and increased expression of Ackr3 mostly in the vascular wall and adventitia of the AAA group." (PMID 40440080, 2025). "For example, the higher expression of Cxcr4 and lower expression of Ackr3 in the aneurysm may contribute to the progression of AAA." (PMID 40440080, 2025).
Arterial thrombosis (2 papers, 2023 to 2025). The formation of a blood clot inside an artery. "High levels of CXCL12 and CXCR4 on the surface of platelets are biomarkers that predict increased cardiovascular mortality due to arterial thrombosis." (PMID 37954596, 2023).
Atrophy (2 papers, 2021). Any weakening or degeneration, especially through lack of use. "Reduced CXCR4 expression showed the anti-inflammatory effect in diabetic rats with cardiac atrophy." (PMID 34512937, 2021).
autism (2 papers, 2024 to 2025). Persistent deficits in social interaction and communication and interaction as well as a markedly restricted repertoire of activity and interest as well as repetitive patterns of behavior. "Preclinical studies have demonstrated that CXCR4 inhibition can normalize excitatory/inhibitory balance and improve social behaviors in mouse models of autism." (PMID 40526590, 2025). "CXCR4, a gene related to astrocyte survival with 3-fold greater expression in astrocytes compared to neurons, showed decreased expression in the astrocytes (80%, p = 0.006) and to a lesser extent in the neurons (28%, p = 0.1) of patients with autism vs. controls." (PMID 38994948, 2024). "Moreover, the astrocytes of patients with autism exhibited higher expression of TGFB1 and TGFB2 but reduced expression of proliferator genes such as CXCR4 and NURR1 in addition to RELN, EN2, HAP1, SIRT1, and GPX1 vs. controls." (PMID 38994948, 2024).
autoimmune hemolytic anemia (2 papers, 2022 to 2023). Autoimmune hemolytic anemia (AIHA) is an autoimmune disorder in which various types of auto-antibodies are directed against red blood cells causing their survival to be shortened and resulting in hemolytic anemia. "Of interest was to observe the resolution of aVWD (all patients had CXCR4 mutations) and autoimmune hemolytic anemia associated with response to ibrutinib." (PMID 34531537, 2022).
bladder tumor (2 papers, 2022 to 2024). "Although the expression of CXCR4 in human bladder tumor samples correlates with tumor stage and is expressed highest in invasive bladder tumors, these results suggest a possible marker for the metastatic capacity of bladder tumors." (PMID 39409924, 2024). "Moreover, the expression levels of RON and CXCR4 exhibited a marked correlation with the progression of bladder tumor stage." (PMID 36103228, 2022).
carcinoid (2 papers, 2015 to 2017). "Global gene expression profiling of GOT1 ileal carcinoid cells revealed a marked upregulation of CXCR4 in response to hypoxia, and the agonist stimulation of CXCR4 was able to activate the mitogen-activated protein kinase (MAPK) p42/44 pathway, resulting in increased tumor cell migration." (PMID 28186979, 2017). "CXCR4 expression was evaluated in a panel of bronchopulmonary neuroendocrine neoplasms (BP-NEN) comprising typical carcinoids (n = 26), atypical carcinoids (n = 30), and small cell lung cancers (SCLC, n = 34)." (PMID 25671300, 2015).
cervical tumor (2 papers, 2014 to 2021). "A cervical tumor invades in adjacent tissues and subsequently into distant organs initiated by the expression of CXCR4 through the link of another factor CXCL12." (PMID 33946372, 2021). "The present study demonstrates that downregulated expression of CXCR4 in CC cell lines and primary cervical tumors is due to promoter hypermethylation." (PMID 25114911, 2014).
chronic nasopharyngitis (2 papers, 2014 to 2026). "In chronic nasopharyngitis tissues (inflammation), epithelial cells showed weak SDF-1 and CXCR4 immunoreactivity (left)." (PMID 24877105, 2014).
cutaneous T cell lymphoma (2 papers, 2020 to 2021). "For example, CCL18 decreases the proliferation of acute lymphocytic leukemia B cells and cutaneous T-cell lymphoma (CTCL) in a process dependent on GPR30 that affects the activity of CXCR4." (PMID 33076281, 2020).